EBP (EBP cholestenol delta-isomerase)
Description:
Isomerase that catalyzes the conversion of Delta(8)-sterols to their corresponding Delta(7)-isomers a catalytic step in the postlanosterol biosynthesis of cholesterol. Component of the microsomal antiestrogen binding site (AEBS), a multiproteic complex at the ER membrane that consists of an association between EBP and 7-dehydrocholesterol reductase/DHCR7. This complex is responsible for cholesterol-5,6-epoxide hydrolase (ChEH) activity, which consists in the hydration of cholesterol-5,6-epoxides (5,6-EC) into cholestane-3beta,5alpha,6beta-triol (CT). The precise role of each component of this complex has not been described yet.
Synonyms: D8D7I; CPX; CPXD; CHO2; CDPX2; MEND
Tractability: Small molecule: a structure with a bound ligand is known; a high-quality ligand is known; it belongs to a druggable protein family. Antibody: UniProt predicts a signal peptide or a membrane-spanning region. PROTAC: ubiquitination databases record sites on it; its protein half-life has been measured; a small molecule that binds it is known.
Target class: Isomerase; Enzyme
Gene: Protein-coding gene on chromosome X (48,521,089 to 48,528,716, forward strand). Ensembl gene ENSG00000147155.
Subcellular location: Endoplasmic reticulum membrane; Nucleus envelope; Cytoplasmic vesicle
Subcellular location (Human Protein Atlas): Endoplasmic reticulum; Nuclear membrane
Pathways (Reactome):
Metabolism: Cholesterol biosynthesis from zymosterol (modified Kandutsch-Russell pathway); Cholesterol biosynthesis via desmosterol (Bloch pathway)
Gene Ontology:
Molecular function: cholestenol delta-isomerase activity; cholesterol-5,6-oxide hydrolase activity; identical protein binding; protein binding; steroid Delta-isomerase activity; C-8 sterol isomerase activity; intramolecular oxidoreductase activity, transposing C=C bonds
Biological process: cholesterol biosynthetic process; cholesterol metabolic process; ossification involved in bone maturation; sterol metabolic process
Cellular component: cytoplasmic vesicle; endoplasmic reticulum; endoplasmic reticulum membrane; nuclear envelope; nuclear membrane; membrane
Gene-disease validity (ClinGen):
ClinGen rates the evidence that EBP causes each of these diseases.
MEND syndrome (X-linked): Definitive.
Homologues: Orthologues: chimpanzee EBP (99% identical), pig EBP (88% identical), rat Ebp (81% identical), mouse Ebp (78% identical), guinea pig EBP (73% identical), dog EBP (69% identical), zebrafish ebp (58% identical). Paralogues in human: EBPL (23% identical).
Diseases named in the same sentence as EBP in open-access papers:
EBP is named in the same sentence as 65 diseases in open-access papers, as found by Europe PMC text mining. Sharing a sentence is not in itself a finding about the gene and the disease. The quoted sentences say what the papers report.
X-linked dominant chondrodysplasia punctata (6 papers, 2011 to 2025). X-linked dominant chondrodysplasia punctata (CDPX2) is a rare genodermatosis with great phenotypic variation and characterized most commonly by ichthyosis, chondrodysplasia punctata (CDP), asymmetric shortening of the limbs, cataracts and short stature. "Human mutations in EBP cause X-linked dominant chondrodysplasia punctata (CDPX2, Conradi-Hunermann syndrome)." (PMID 21912524, 2011). "Syndromes such as Ichthyosis folliculareis–alopecia–photophobia (IFAP), X-linked dominant chondrodysplasia punctata (CDPX2) and Congenital hemidysplasia with ichthyosiform erythroderma and limb defects (CHILD Syndrome) result from mutations in the MBTPS2, EBP and NSDHL genes, respectively." (PMID 41305004, 2025).
breast carcinoma (5 papers, 2003 to 2020). "Here, we report two crystal structures of human EBP, one in complex with the anti-breast cancer drug tamoxifen and the other in complex with the cholesterol biosynthesis inhibitor U18666A." (PMID 31165728, 2019). "In the breast cancer MCF-7 cell line and MCF-7-derived cell lines, significant amounts of both EBP and SR-BP were obtained from 40 000 to 280 000 and 5 000 to 80 000 sites cell−1, respectively." (PMID 12569389, 2003).
chondrodysplasia punctata (4 papers, 2014 to 2025). A rare congenital developmental disorder characterized by the presence of stippled foci of calcification in the hyaline cartilage, joint contractions, mental retardation and ichthyosis. "EBP mutations are the cause of chondrodysplasia punctata 2 X-linked dominant (CDPX2), also known as Conradi-Hünermann-Happle syndrome, a defective cholesterol biosynthesis disorder." (PMID 25566323, 2014). "Conradi‐Hünermann‐Happle syndrome (CHHS) or X‐linked dominant chondrodysplasia punctata (CDPX2, OMIM 302960) is a rare type of chondrodysplasia punctata associated with X‐linked dominant variants in the emopamil binding protein (EBP) gene, which impairs cholesterol biosynthesis." (PMID 40889793, 2025).
Conradi-Hunermann syndrome (4 papers, 2011 to 2025). "Biochemical studies on Conradi–Hunermann syndrome patients demonstrated increased amounts of 8,9-unsaturated sterols in the plasma and tissues due to mutations in the EBP gene." (PMID 31165728, 2019). "Notably, pathogenic variants in the EBP gene have been found to cause X-linked chondrodysplasia punctata 2, a developmental disability sharing some phenotypic features with SLOS." (PMID 40305315, 2025).
colorectal cancer (3 papers, 2023 to 2025). A primary or metastatic malignant neoplasm that affects the colon or rectum. "The results reveal that most of the identified essential genes were compatible with the colorectal cancer cell lines obtained from DepMap and that these genes, with the exception of EBP, LSS, and SLC7A6, could generate a high level of cell death when knocked out." (PMID 37205704, 2023). "TASINs were found to inhibit EBP, DHCR7, and DHCR24, leading to colorectal cancer cell death." (PMID 38672427, 2024).
glioma (3 papers, 2020 to 2023). A benign or malignant brain and spinal cord tumor that arises from glial cells (astrocytes, oligodendrocytes, ependymal cells). "A glioma cell line derived from these tumors (named C266) was used to investigate its dependency on the EBP protein and susceptibility to clemastine, benztropine, and a small-molecule drug (CW3388) known to inhibit mouse EBP." (PMID 37760589, 2023). "Second, the essentiality of EBP in BTICs needs to be assessed and validated in vivo by performing limiting dilution experiments using the isogenic Ebp-knockdown mouse glioma cell line in our mouse models." (PMID 37760589, 2023). "ATP-binding cassette transporter (ABCE1), being a chaperone, associates with chemotherapy resistance in glioma via PI3K/Akt/NF-κB pathway form PPIs with EBP and FDPS enzymes." (PMID 34440098, 2021). "Comet assays also illustrated that BIP-MPC-NP enhanced the DNA damage induced by TMZ compared with EBP-MPC-NP or MBP-MPC-NP in TMZ-resistant glioma cells." (PMID 32001707, 2020). "With nanoinhibitors as treatments on TMZ-resistant glioma cells, BIP-MPC-NP simultaneously attenuated p-EGFR and p-MET in cells with EGF and HGF incubation or without EGF and HGF incubation, and this attenuation was more significant than that of EBP-MPC-NP or MBP-MPC-NP group." (PMID 32001707, 2020).
prostate carcinoma (3 papers, 2003 to 2025). A carcinoma that arises from epithelial cells of the prostate gland. "In an attempt to correlate the growth-inhibitory activity of SR31747A with the presence of its receptors, we evaluated EBP and SR-BP expression levels by flow cytometry using specific antibodies in the breast and prostatic cancer cell lines used in this study." (PMID 12569389, 2003). "Inhibition of EBP has been shown to inhibit prostate cancer cell proliferation." (PMID 40405591, 2025). "On the other hand, EBP inhibitors have been shown to impair prostate cancer proliferation." (PMID 38927057, 2024). "In prostatic cancer cell lines, 40 000 EBP sites cell−1 were measured." (PMID 12569389, 2003).
MEND syndrome (2 papers, 2022 to 2025). "In the current study, we identified and computationally characterized a novel EBP variant segregating in X-linked recessive mode in a family affected with MEND syndrome." (PMID 39754633, 2025). "Moreover, only six EBP variants underlying MEND syndrome are reported in the literature." (PMID 39754633, 2025). "It strengthens the body of evidence that supports the role of EBP in the MEND syndrome phenotype." (PMID 39754633, 2025).
Obesity (2 papers, 2016 to 2022). Accumulation of substantial excess body fat. "Surprisingly, SCD1, DGAT1 and EBP were downregulated by LPS, as LPS have previously been described to initiate obesity." (PMID 27438462, 2016).
Smith-Lemli-Opitz syndrome (2 papers, 2020). Smith-Lemli-Opitz syndrome (SLOS) is characterized by multiple congenital anomalies, intellectual deficit, and behavioral problems. "Similarly, patients with Smith-Lemli-Opitz syndrome, which results from mutations in the 7-dehydrocholesterol reductase (DHCR7) gene, and CDPX2, a result of mutations in the EBP gene, often present with normal cholesterol levels and elevated levels of sterol intermediates." (PMID 32430393, 2020).
adenoma (1 paper, 2012). A neoplasm arising from the epithelium. "Together, these results suggested that A-C/EBP expression in the presence of Dox may interfere with malignant conversion of adenoma to carcinoma in A-C/EBP+ mice." (PMID 23234329, 2012).
Allergy (1 paper, 2023). An allergy is an immune response or reaction to substances that are usually not harmful. "In this study, we found that clemastine, an over-the-counter oral medication for allergy relief, attenuated the propagation and promoted the differentiation of BTICs, and we uncovered the indispensable role of EBP (Emopamil-binding protein) in maintaining the BTIC population." (PMID 37760589, 2023).
atopic dermatitis (1 paper, 2024). "In atopic dermatitis, genes mainly related to lipid metabolism (e.g. ACAD8, FADS6, or EBP) as well as disease-specific genes, i.e., Th2 inflammation-related lipid-regulating HSD3B1 were differentially expressed." (PMID 38433843, 2024).
cerebral infarction (1 paper, 2024). An ischemic condition of the brain, producing a persistent focal neurological deficit in the area of distribution of the cerebral arteries. "Finally, the antiapoptotic ability of ECM and EBP-bFGF was further validated in rats at 14 d of cerebral infarction." (PMID 38715911, 2024).
Cerebral ischemia (1 paper, 2024). Restriction of arterial blood supply to the brain associated with insufficient oxygenation to support the metabolic requirements of the tissue. "Transcriptome analysis was used to determine the EBP-bFGF/ECM-mediated repair mechanism in rats with cerebral ischemia." (PMID 38715911, 2024). "In addition, the underlying mechanism of EBP-bFGF/ECM was explored by transcriptome analysis and the neuroprotective NRG1/AKT signaling pathway involved in the repair of cerebral ischemia." (PMID 38715911, 2024). "Furthermore, the EBP-bFGF was used for bioactive modification of ECM hydrogel to repair cerebral ischemia." (PMID 38715911, 2024). "Finally, the potential molecular mechanism of EBP-bFGF/ECM involved in the restoration of cerebral ischemia was explored by RNA sequencing and transcriptome analysis." (PMID 38715911, 2024). "Combined with the neuron immunostaining, it was reasonably speculated that EBP-bFGF/ECM had significant neuroprotective effects and might also be involved in activating NPCs, further facilitating the regeneration and repair of cerebral ischemia." (PMID 38715911, 2024).
chondrodysplasia (1 paper, 2021). "Loss-of-function mutations in EBP on the X-chromosome have been previously identified in Conradi-Hünermann-Happle-syndrome, which is also known as X-linked dominant chondrodysplasia punctata 2 (CDPX2) (OMIM #302960)." (PMID 34093655, 2021).
coronary heart disease (1 paper, 2025). "ATP7A and PHKA1 are likely related to the cardiovascular system, EBP is associated with coronary heart disease and skeletal-related conditions, ZFX is known to be involved in animal size and ovarian failure, and SMC1A is implicated in premature ovarian failure." (PMID 39940742, 2025).
cutaneous sarcoidosis (1 paper, 2024).
Hyperglycemia (1 paper, 2015). An increased concentration of glucose in the blood. "It has been demonstrated that hyperglycemia upregulates ET-1 in endothelial cells by mediating through AMPK-C/EBP signaling pathway." (PMID 26692905, 2015).
liposarcoma (1 paper, 2008). A usually painless malignant tumor that arises from adipose tissue. "Interestingly, we found high levels of eIF4E and eIF2α in liposarcomas, two translation initiation factors involved in controlling the ratio of C/EBP isoforms." (PMID 18596980, 2008).
liver cancer (1 paper, 2024). An epithelial or non-epithelial malignant neoplasm that arises from the liver. "After analyzing six tumor-specific signatures (IDI1, GMPPA, NME1, PSMB3, SPTLC1 and EBP), the gene effect and gene dependency were measured in different non-cancerous cell lines and liver cancer lines of human HCC." (PMID 38927057, 2024).
lung carcinoma (1 paper, 2012). "Indeed, expression of NR1H3 (LXR-α) showed a significant correlation with FDPS and EBP synthesis in lung cancer samples but not in normal lung samples (data not shown), suggesting a cancer-specific regulation of mevalonate pathway genes by LXR-α." (PMID 22211244, 2012).
metastatic prostate carcinoma (1 paper, 2025). A carcinoma that arises from the prostate gland and has spread to other anatomic sites. "The eight genes where higher expression was associated with worse prognosis (CYC, CYP51A1, DHFR, EBP, KIF15, PPM1D, SQLE, and UMPS) represent potential additional therapeutic targets in metastatic prostate cancer." (PMID 40405591, 2025). "Eight genes (CYC, CYP51A1, DHFR, EBP, KIF15, PPM1D, SQLE, and UMPS) demonstrated strong dependency in cell lines and were also associated with worse prognosis clinically, representing potential therapeutic targets in metastatic prostate cancer." (PMID 40405591, 2025).
Stroke (1 paper, 2024). Sudden impairment of blood flow to a part of the brain due to occlusion or rupture of an artery to the brain. "In the following studies, the degradation of EBP-bFGF/ECM hydrogel in stroke cavity in vivo will be explored to further validate the relationship between ECM degradation and EBP-bFGF-induced tissue regeneration." (PMID 38715911, 2024).
thymoma (1 paper, 2021). A neoplasm arising from the epithelial cells of the thymus. "R-values were mostly positive, however, a negative correlation was observed for PPIs with participation of EBP in thymoma tissues (339 and 118 normal and tumor cases, respectively)." (PMID 34440098, 2021).
vivax malaria (1 paper, 2017). "The majority of the antigens associated with protection against vivax malaria in this cohort were newly described or understudied, such as EBP, P41, CyRPA, RBP1a, and RBP2b." (PMID 28949293, 2017).
cancer (15 papers, 2003 to 2025). A tumor composed of atypical neoplastic, often pleomorphic cells that invade other tissues. "EBP is the essential enzyme required for cholesterol biosynthesis, and inhibition of EBP led to cancer cell death via depletion of downstream sterols." (PMID 35957912, 2022). "In our previous study, we identified that the VEGF-C/VEGFR-3 axis-mediated invasion of human cancer cells required the activation of the Src-p38-C/EBP-dependent pathway." (PMID 25003617, 2014). "To test this hypothesis, we investigated the expression levels of both SR-BP and EBP in the series of cancer cell lines included in our study." (PMID 12569389, 2003). "In cancer, DHCR7 inhibition elevates 7‐DHC, suppressing ferroptosis but paradoxically promoting metastasis, while targeting upstream enzymes (e.g., EBP) to deplete 7‐DHC induces ferroptosis and inhibits tumor growth." (PMID 41198144, 2025). "Other MS loci display marked cancer-type specificity, for example, MSI events within the 5′ UTR region of ZNF738, C10orf140, ZNF271 and RAB28 are specific to COAD tumours, whereas those in EBP, TMEM182, MIR567 and MEIS1 are absent or substantially depleted in STAD compared to COAD and UCEC tumours." (PMID 28585546, 2017).
tumor (7 papers, 2017 to 2025). "Third, illustrating the molecular mechanisms of the tumor suppressive effects of EBP inhibition will be critical for assessing the potential of this enzyme as a therapeutic target." (PMID 37760589, 2023). "It is possible that EBP inhibition alters the intermediate metabolite composition in tumor cells (cell-autonomous) and/or in the tumor microenvironments (e.g., non-tumor cells)." (PMID 37760589, 2023). "Finally, we showed that pharmacological targets of clemastine, as highlighted by EBP, are essential for the proliferation of these tumor cells." (PMID 37760589, 2023). "In addition, mice treated with EBP‐ or MBP‐MPC‐NP for 21 days showed 75% reduction in tumor volume to 50 mm3, further demonstrating the enhanced anti‐tumor effect of combination therapy." (PMID 34085418, 2021). "Blocking EBP activity has been shown to contribute to the death of tumor cells." (PMID 31165728, 2019). "Notably, EBP binds an abundance of structurally diverse pharmacologically active compounds, including antidepressants, antipsychotics, opioid analgesics, sterol biosynthesis inhibitors and anti-tumor reagents." (PMID 31165728, 2019).
skeletal dysplasia (3 papers, 2019 to 2025). Any Mendelian diseases that affects growth and development of the skeleton. "Four variants were highlighted in four genes known to cause skeletal dysplasias, namely EBP, INPPL1, COL1A2, and SLC26A2, being the last two characterised by high in utero lethality." (PMID 41153384, 2025). "Genetic testing using whole exome sequencing (WES) based on next-generation sequencing (NGS), targeting a panel of genes associated with skeletal dysplasia, revealed a loss-of-function variant in the emopamil-binding protein (EBP) gene." (PMID 39803055, 2024). "X-linked dominant chondrodysplasia punctata type 2 (CDPX2) is a condition involving facial, skin, and skeletal dysplasia as a result of a mutation in emopamil binding protein (EBP)." (PMID 30608402, 2019). "The CDPX2 is a type of skeletal dysplasia caused by EBP mutations." (PMID 30608402, 2019).
EBP also shares sentences with these, for which no sentence is quoted: CHILD syndrome (4 papers); alopecia (2); cataract (2); infection (2); amyotrophic lateral sclerosis (1); Anxiety (1); brain cancer (1); colon cancer (1); depression (1); desmosterolosis (1); developmental disability (1); familial amyloid polyneuropathy (1); Granuloma (1); Greenberg dysplasia (1); hypotrichosis (1); ichthyosiform erythroderma (1); ichthyosis (1); lathosterolosis (1); lipodystrophy (1); major depressive disorder (1); malaria (1); metabolic disease (1); Micro syndrome (1); microcephaly (1); multiple sclerosis (1); Nonalcoholic steatohepatitis (1); osteogenesis imperfecta type 2 (1); ovarian failure (1); pheochromocytoma (1); premature ovarian failure (1).
A further 6 diseases each share a sentence with EBP in 1 paper.